SLC3A2 (solute carrier family 3 member 2)
Diseases named in the same sentence as SLC3A2 in open-access papers (continued):
Sharing a sentence is not in itself a finding about the gene and the disease.
glioma (continued). "These insights underscore the multifaceted role of SLC3A2 in gliomas progression and the profound influence of SLC3A2 on the success of immune therapies and proposes its viability as a target for immunotherapy." (PMID 38977800, 2024). "Our results indicate a significant increase in SLC3A2 expression in tumor samples compared to normal ones, closely linking it to a poor prognosis in gliomas cases." (PMID 38977800, 2024). "Immunohistochemical analysis has indicated high levels of SLC3A2 expression in tumor tissues, and the highest levels of SLC3A2 expression have been observed in high-grade gliomas." (PMID 38977800, 2024). "Intriguingly, SLC3A2 attenuation significantly curtailed proliferation, invasion, and migratory propensities in U87 and U251 glioma cell lines." (PMID 38977800, 2024). "Moving past computational analysis, we embarked on in vitro experiments to investigate the role of SLC3A2 in glioma pathology." (PMID 38977800, 2024). "Consistent with the TCGA and GEO database findings, an upregulation of SLC3A2 was observed in glioma tissues in our collection of 24 paired tumor and adjacent non-tumor tissues from glioma patients." (PMID 38977800, 2024). "In our evaluation of the risk factors of eight genes, we identified SLC3A2, RPN1, NDUFA11, GYS1 and OXSM as potential risk factors for glioma prognosis." (PMID 38022537, 2023). "The initial cloning of the major LNAA transporter, designated LAT1 (SLC7A5), from a C6 rat glioma line was enabled by the co-expression of 4F2hc (SLC3A2), which forms a hetero-duplex within the membrane with LAT1." (PMID 35745855, 2022). "The oncogenic nature of SLC3A2, demonstrated via both in vitro and in vivo studies, aligns with our bioinformatics findings, highlighting the critical function of SLC3A2 in the development of glioma." (PMID 38977800, 2024). "Overall, these results suggest that SLC3A2 is an oncogene leading to poor outcomes in gliomas." (PMID 38977800, 2024). "Remarkably, SLC7A11 was also one of the related hub genes of SLC3A2, which reinforced the conclusion that SLC3A2 may interact with gliomas through disulfidptosis." (PMID 38977800, 2024). "Furthermore, our investigation has demonstrated that various immune markers and levels of immune infiltration in gliomas are correlated with the expression of SLC3A2." (PMID 38977800, 2024). "Additionally, Cox regression analyses suggest that SLC3A2 independently influences the prognosis of glioma." (PMID 38977800, 2024). "This study aims to clarify the prognostic value of SLC3A2 and its influence on glioma." (PMID 38977800, 2024). "This work delves into the biological relevance of SLC3A2 in gliomas." (PMID 38977800, 2024). "Synthesizing the insights from immune infiltration metrics, single-cell transcriptomics, and M2 marker co-expression analyses, we postulate that SLC3A2 catalyzes a transformative effect on the glioma tumor microenvironment, particularly by steering macrophage polarization towards an M2 phenotype." (PMID 38977800, 2024). "The SLC3A2-related PPI network in gliomas has been constructed using Cytoscape." (PMID 38977800, 2024). "This suggests that upregulation of SLC3A2 may induce disulfidptosis, thereby affecting glioma prognosis and metabolism." (PMID 38977800, 2024). "The forest map shows that these five genes (SLC3A2, RPN1, NDUFA11, GYS1, OXSM) might be high-risk factors for glioma prognosis." (PMID 38022537, 2023). "Moreover, inhibition of glutamate release via system Xc−, consisting of xCT (SLC7A11) and CD98 (SLC3A2, 4F2HC), profoundly decelerates the glioma phenotype in vivo, and in addition mitigates tumor-induced brain swelling and tumor-induced seizures." (PMID 27074570, 2016). "The role of SLC3A2, a gene implicated in disulfidptosis, has not been characterized in gliomas." (PMID 38977800, 2024).
glioma (continued). "In conclusion, SLC3A2 might promote tumor proliferation, progression, metastasis, hemorrhage, and metabolic changes through mechanisms like disulfidptosis, ultimately lowering the overall survival rate of glioma patients." (PMID 38977800, 2024). "Therefore, the inhibition of this pathway by SLC3A2 could lead to glioma hemorrhage, adversely affecting patient survival rates." (PMID 38977800, 2024). "Moreover, diagnostic ROC analysis showcased the superior predictive accuracy of SLC3A2 in gliomas, evidenced by an Area Under the ROC Curve (AUC) of 0.974 (95% CI: 0.967–0.981), affirming its competency in differentiating glioma tissues from normal counterparts." (PMID 38977800, 2024). "Therefore, we concluded that SLC3A2 may be capable of influencing the tumor immune microenvironment of gliomas by regulating M2 macrophages." (PMID 38977800, 2024). "Furthermore, to substantiate the role of SLC3A2 in glioma pathobiology, we performed both in vivo and in vitro experiments, providing a robust experimental framework to confirm our computational prognostic assessments and to explore the therapeutic potential of targeting SLC3A2 in gliomas." (PMID 38977800, 2024). "Importantly, this study elucidated that SLC3A2 expression may regulate glioma development through the process of disulfidptosis." (PMID 38977800, 2024). "However, SLC3A2 was also enriched in immune cells as in glioma, which suggested that SLC3A2 may be involved in some molecular function in immune cells." (PMID 35992269, 2022). "To validate our in vitro results, we assessed the expression of SLC3A2, SLC7A5, and ATB0,+ in tumors obtained from HGG13 glioma-implanted mice." (PMID 37349515, 2023). "The upregulation of disulfidptosis related genes SLC3A2 and SLC7A11 promotes the occurrence and progression of glioma tumors, therefore, a signal target of disulfidptosis may be used in the therapeutic schedule for neurogliomas." (PMID 40109666, 2025). "The specific function of SLC3A2 in gliomas, however, is not entirely clear." (PMID 38977800, 2024).
lung adenocarcinoma (15 papers, 2021 to 2025). A carcinoma that arises from the lung and is characterized by the presence of malignant glandular epithelial cells. "Elevated serum levels of SLC3A2 have been detected in patients with lung adenocarcinoma (LUAD) and lung squamous cell carcinoma (LUSC), which also corresponded to the increased mRNA level of SLC3A2 in cancer tissues." (PMID 41154605, 2025). "SLC3A2 acts as a metabolic switch on lung adenocarcinoma cells to induce macrophage phenotypic reprogramming through arachidonic acid." (PMID 41440381, 2025). "Studies have shown that high expression of SLC3A2 is closely related to the growth, invasion, and metastasis of various malignancies, such as lung adenocarcinoma and colorectal cancer." (PMID 39896807, 2024). "Another study suggests that the low-density solute carrier family 3 member 2 (SLC3A2) induces macrophage phenotypic reprogramming through arachidonic acid in lung adenocarcinoma." (PMID 39170251, 2024). "Additional research has revealed that m6A reader YTHDC2 contributes to ferroptosis in lung adenocarcinoma by targeting SLC3A2." (PMID 36359826, 2022). "A for the relationship between ferroptosis and m6A modification, the m6A reader YTHDC2 serving as ferroptosis inducer was proved to regulate SLC3A2 in lung adenocarcinoma." (PMID 35127813, 2021). "In hepatocellular carcinoma, IGF2BP3 stabilizes NRF2 mRNA to inhibit ferroptosis; whereas in lung adenocarcinoma, it modulates multiple anti-ferroptotic regulators such as GPX4, SLC3A2, ACSL3, and FTH1 to confer ferroptosis resistance." (PMID 40530014, 2025). "SLC3A2 and SLC7A11 are two subunits of system XC−, and are the targets of the m6A reader YTHDC2 to execute ferroptosis in lung adenocarcinoma cells." (PMID 37714846, 2023). "The protein expression of SLC3A2, SLC11A2, SLC1A5, SLC16A1, SLC39A7, SLC39A14 in the lung adenocarcinoma cell line A-549 and H1299 is higher than that in the normal lung epithelial cell line Beas-2B." (PMID 37973895, 2023). "IGF2BP3 inhibited ferroptosis by binding to m6A methylated mRNA encoding anti-ferroptotic factors, including glutathione peroxidase 4 (GPX4), solute carrier family 3 member 2 (SLC3A2), and ferritin heavy chain H1 (FTH1), in lung adenocarcinoma cells." (PMID 36835633, 2023). "The gene expression of SLC3A2, SLC16A1, SLC39A14, SLC39A7, SLC1A5, and SLC11A2 in the lung adenocarcinoma cell line A-549 and H1299 is higher than that in the normal lung epithelial cell line Beas-2B." (PMID 37973895, 2023). "In this study, we analyzed SLC3A2 mRNA levels in human lung squamous cell carcinoma (LUSC) and lung adenocarcinoma (LUAD) using the TCGA database and serum SLC3A2 protein levels using ELISA." (PMID 36358610, 2022). "IGF2BP3 could stabilize a spectrum of anti-ferroptosis mRNA, including glutathione peroxidase 4 (GPX4), solute carrier family 3 member 2 (SLC3A2), acyl-CoA synthetase long chain family member 3 (ACSL3), and ferritin heavy chain 1 (FTH1), to inhibit ferroptosis in lung adenocarcinoma cells." (PMID 37554271, 2023).
pancreatic cancer (13 papers, 2008 to 2025). "We performed in vitro experiments to validate that SLC3A2 knockdown could improve the sensitivity to ferroptosis in a colorectal cancer cell-line and a pancreatic cancer cell-line." (PMID 35992269, 2022). "Similarly to studies indicating that 4F2hc (SLC3A2) is overexpressed during the progression of breast and pancreatic cancer, we detected significantly increased transcript levels of Slc3a2 in BRAFV600E/PIK3CAH1047R double-mutant tumors." (PMID 30241549, 2018). "We further performed qRT-PCR on five selected ferroptosis-related genes (HMOX1, CHAC1, SLC3A2, SLC7A11, and FTH1) in pancreatic cancer cells after 12 and 24 h of CBC treatment." (PMID 40790027, 2025). "SLC7A5 and SLC3A2 expression is highly upregulated in many tumor types, such as HNSCC, prostate, lung, breast, and pancreatic cancers." (PMID 33401748, 2021). "By analyzing the Cancer Therapeutics Response Portal (CTRP) database, we found that the elevated gene expression of SLC3A2 was positively correlated with resistance to GPX4 inhibitors such as RSL3, ML162, and ML210, especially in RLS3-treated pancreatic cancer cell lines." (PMID 37479744, 2023). "The genetic disruption or chemical inhibition of SLC3A2/ SLC7A11 HATC leads to autophagy and ferroptosis in the different types of tumor cells, including endometrial, colorectal, pancreatic cancer, and hepatocellular carcinoma (HCC) through inhibition of mTOR/p70S6K signaling." (PMID 33401748, 2021). "Moreover, by analysing transcriptomics and proteomics datasets of human PDAC, we found that Slc3a2 and Lamin B1 were significantly elevated in PDAC tissue when compared to the normal tissue counterpart, thus indicating a positive role of these genes in pancreatic cancer progression." (PMID 39587609, 2024). "Finally, NRG1 fusion partners were most commonly ATP1B1 (pancreatic cancer) or CD74 (NSCLC) in FDA-approved indications, with a mix of these as well as SLC3A2 and RBPMS being commonly observed partner genes in nonapproved indications." (PMID 41091579, 2025).
colorectal cancer (12 papers, 2019 to 2025). A primary or metastatic malignant neoplasm that affects the colon or rectum. "As one member of system xc-, SLC3A2 has been found involved in ferroptosis, metabolism and proliferation of several tumors, including BC, colorectal cancer, melanoma, gastroenteropancreatic-neuroendocrine neoplasm, leukaemia and prostate cancer 8-13." (PMID 37484811, 2023). "Our study demonstrated that inhibition SLC3A2 significantly suppressed the proliferation, migration and invasion of colorectal cancer cells in vitro, and inhibited tumour progression in vivo." (PMID 35567291, 2022). "In conclusion, our study revealed that MIF participates in the phenotypic regulation of colorectal cancer cells by targeting SLC3A2." (PMID 35567291, 2022). "We found that the levels of MIF and SLC3A2 mRNA and protein expression were notably increased in the colorectal cancer cells (SW480, SW620, HCT116, HT‐29 and LoVo) when compared with normal epithelial cells (NCM460, FHC)." (PMID 35567291, 2022). "Results showed that the levels of MIF and SLC3A2 expression were up‐regulated in colorectal cancer cells." (PMID 35567291, 2022). "We will continue to explore the roles and mechanisms of MIF and SLC3A2 in colorectal cancer, so as to provide a basis for targeting those molecules in the clinical treatment of colorectal cancer." (PMID 35567291, 2022). "This study investigated the mechanisms of migration inhibitory factor (MIF) and solute carrier family 3 member 2 (SLC3A2) in colorectal cancer progression." (PMID 35567291, 2022). "Additionally, our in vivo results verified that MIF regulates the biological behaviour of colorectal cancer cells by targeting SLC3A2 and regulating the AKT/GSK‐3β signalling pathway." (PMID 35567291, 2022). "Finally, a nude mouse tumorigenicity assay was used to confirm the functions of MIF and SLC3A2 in colorectal cancer." (PMID 35567291, 2022). "In our study, we found that MIF (a soluble factor) could directly bind to SLC3A2 (a membrane‐binding factor) and regulate the function of colorectal cancer cells by promoting SLC3A2 expression." (PMID 35567291, 2022). "MIF and SLC3A2 might be potential biomarkers for monitoring the treatment of colorectal cancer." (PMID 35567291, 2022). "Co-expression analyses of the TCGA and CPTAC colorectal cancer cohorts identified a network of gene transcripts positively related to SLC7A5, with its heterodimer partner SLC3A2 having the highest co-expression score." (PMID 38722983, 2024). "The transcription of SLC7A11, SLC3A2, SLC1A4, and SLC1A5 in colorectal cancer cells were all activated under hypoxia condition." (PMID 39079386, 2024). "By analyzing the mRNA expression of SLC1A5, SLC3A2, and SLC7A5 in human colon cancer samples deposited in The Cancer Genome Atlas (TCGA) database (n = 41 matched pairs of normal and colorectal cancer samples), we found that all three genes had elevated expression in nearly all patients." (PMID 31416966, 2019).
gastric cancer (12 papers, 2017 to 2025). A primary or metastatic malignant neoplasm involving the stomach. "Taken together, we demonstrated that SLC3A2 was the target antigen of an anti-gastric cancer mAb 3G9 and increased expression of SLC3A2 associated with serosal invasion of GC." (PMID 29179459, 2017). "Protein SLC3A2 is associated with the migration and invasion of tumor cells, which is a potential biomarker for molecular imaging-based detection of gastric cancer." (PMID 33425983, 2020). "Coincidentally, it has been reported that SLC3A2 expression is significantly increased in gastric cancer cell lines and tumour tissues, and those increases are related to serosal invasion." (PMID 35567291, 2022). "Further immunoblotting analysis with 3G9 to the immunoprecipitation products also confirmed the antigen as SLC3A2, which were identical to that of in the gastric cancer cells." (PMID 29179459, 2017). "In the present study, we confirmed the specific antigen of mAb 3G9 as SLC3A2 by immunoprecipitation followed by mass spectrometry analysis and discuss the role of SLC3A2 on gastric cancer metastasis." (PMID 29179459, 2017). "In this study, we identified the target antigen of mAb 3G9 as SLC3A2, and detected the expression profile of SLC3A2 in a panel of gastric cancer cell lines and GC tumor tissues." (PMID 29179459, 2017). "Here, it is not the cell proliferation but the colony formation ability was obviously changed when the expression of SLC3A2 was altered in gastric cancer cells." (PMID 29179459, 2017). "Moreover, several researches reported that SLC3A2 was highly expressed in gastric cancer, osteosarcoma, renal cell carcinoma, and biliary tract cancer 35-38." (PMID 35371305, 2022). "Moreover, gene FBXO11, XPO1, SLC3A2, and APC, whose mutation detections may be affected by various tumor purities in gastric cancer, were closely related with cancer occurrence and development." (PMID 33425983, 2020). "Thus, SLC3A2 might play regulatory role in GC malignant phenotype and serve as a potential biomarker of gastric cancer." (PMID 29179459, 2017). "However, the function of SLC3A2 in gastric carcinoma (GC) has not been well explored." (PMID 29179459, 2017).
osteosarcoma (12 papers, 2018 to 2026). A usually aggressive malignant bone-forming mesenchymal neoplasm, predominantly affecting adolescents and young adults. "SLC3A2, an integrin-associated protein, was shown to be up-regulated in osteosarcoma samples and cell lines, and its expression was linked to tumor size and stage in osteosarcoma." (PMID 35518353, 2022). "For instance, SNHG1 could interact with the mediator complex of solute carrier family 3 member 2 (SLC3A2) as a cancer-promoting factor and progress gastric and osteosarcoma malignancies." (PMID 35096086, 2022).
hepatocellular carcinoma (11 papers, 2016 to 2025). A malignant tumor that arises from hepatocytes. "Similarly, exosome-released miR-142-3p from hepatocellular carcinoma (HCC) cells targets SLC3A2 expression, inducing ferroptosis in M1 macrophages." (PMID 40328736, 2025). "Conversely, microRNA-142-3p promotes ferroptosis in Hepatitis B Virus -infected M1 macrophages via Solute Carrier Family 3 Member 2 (SLC3A2), affecting GSH and Fe2+ production, which accelerates the progression of hepatocellular carcinoma." (PMID 41326356, 2025).
melanoma (11 papers, 2021 to 2026). A malignant, usually aggressive tumor composed of atypical, neoplastic melanocytes. "Consistently, low expression of SLC3A2 is associated with good prognosis of patients with melanoma." (PMID 34742351, 2021). "Human melanoma tissues with higher CD8+ T cell infiltration is characterized by lower levels of SLC7A11/SLC3A2, and higher ferroptosis response signature (a gene set that was upregulated by ferroptosis)." (PMID 34742351, 2021). "In concordance, the identified SLC3A2 peptides were demonstrated at significantly higher levels in melanoma vs normal skin (p<0.05, data from three normal skin and two melanoma samples tested twice each in two independent experiments)." (PMID 34112739, 2021). "The average peak area of binding to melanoma cells and normal skin across two independent experiments was significantly higher in malignant cells for SLC3A2, demonstrating highest expression of the target in tumor samples." (PMID 34112739, 2021). "The negative association between CD8+ T cell infiltration, IFN-γ expression, and the expression of SLC3A2 and SLC7A11 was also shown in human melanoma tissues." (PMID 35795206, 2022). "Separately, 18 peptides from two human melanoma lesion samples and 16 peptides from the IGROV1 cell line identified recognition of SLC3A2 by the antibody." (PMID 34112739, 2021). "Compared to melanoma patients who did not benefit from PD-1 blockade, those who show clinical benefit have downregulated expression of SLC3A2 during treatment." (PMID 34742351, 2021). "Notably, 91.7% of SKCM showed upregulated SLC3A2 expression and 16.7% melanoma did not express SLC3A2 or showed a low expression level." (PMID 35992269, 2022).